CD44 (CD44 molecule (IN blood group))
Diseases named in the same sentence as CD44 in open-access papers (continued):
Sharing a sentence is not in itself a finding about the gene and the disease.
breast carcinoma (continued). "The CSC2 number would be related to the niche volume, nutriments and oxygen quantities: in mammary carcinomas, ALDH1+ CD44- Ki67+ CSCs (CSC2s) constitute about 5.54% of the tumor mass and lie in a sub-central site, physically distinct from ALDH1+ CD44+ Ki67+ CSCs (CSC1s)." (PMID 30899759, 2019). "MMPs, ADAMs, HES1/2, HEY1, c-Myc, CD44, EpCAM and Vimentin (downregulation of E-cadherin) engage in survival, stemness, EMT, invasion, ECM degradation/remodeling, angiogenesis, intravasation/extravasation, and metastatic colonization in breast cancer." (PMID 31694640, 2019). "Besides, DOX/CXB mixture and HPPD nanoparticles both enhanced the cytotoxicity of DOX, confirmed that CD44-mediated cellular internalization and COX-2 inhibition contribute to overcome drug resistance in breast cancer." (PMID 31623608, 2019). "Although it has long been recognized that ALDH+ and CD44+/CD24− cells are breast cancer TICs9,12,20,21, their oncogenic properties have not been carefully compared within the same cancer cell population." (PMID 30659204, 2019). "Furthermore, Met, CD44, and TCF1/7 were also preferentially expressed in BLBC clinical samples while Cyclin D1 was preferentially expressed in luminal breast cancer clinical samples." (PMID 31462314, 2019). "Subsequent studies have identified CD44, CD133, and ALDH as CSC markers in breast cancer." (PMID 31137841, 2019). "We have shown previously that a distinct CD44+/CD24- sub-population of breast cancer CTCs is not detectable by CellSearch® (“stem-like” CTCs)." (PMID 31003475, 2019). "Due to its more restricted expression compared with other CSC markers such as CD44 and aldehyde dehydrogenase (ALDH), CD133 has long been considered the most rigorous indicator of malignant precursors in different solid tumors, including breast cancer." (PMID 31636668, 2019). "Given that HA is a natural ligand for CD44, which is often over-expressed by breast cancer cells, we believed that HPPDC nanoparticles could circumvent the efflux effect of P-gp to deliver DOX and CXB through CD44-mediated endocytosis." (PMID 31623608, 2019). "Breast cancer was the first human solid tumor proven to consist of heterogeneous populations of cells: non-CSCs and CSCs; specifically the CSCs subpopulation (CD44+ CD24−/low) is capable of initiating tumor growth in immune-deficient mice." (PMID 30728463, 2019). "We found that the proportion of CD44+ MDA-MB-231 cells was ~12-folds higher in 3D hybrid scaffold compared to scaffold and GelMA alone, indicating that 3D hybrid scaffold strikingly influenced the phenotypic changes of breast cancer cells." (PMID 31222037, 2019). "Therefore, understanding the changes in the expression patterns of CD44 and CD24 in breast cancer after chemotherapy treatment is important for greater understanding of the clinicopathological properties of breast cancer." (PMID 31357721, 2019). "The breast cancer cell lines we used to conduct our experiments—namely, MCF-7 and MDA-MB-468—contained a functional CD44+CD24-/low cancer stem cell subpopulation, as per the published literature and our own preliminary experiments had indicated (data not shown)." (PMID 31627418, 2019). "The study of CD44/CD24 and ALDH1 expression could be the most appropriate to identify BCSCs with distinct levels of differentiation from breast cancer populations." (PMID 31505803, 2019). "Moreover, in primary human luminal breast cancer, the metastasis-initiating cells containing CTC that express EPCAM, CD44, CD47, and the proto-oncogene MET are related with reduced overall survival (OS)." (PMID 31261917, 2019). "Collectively, these data demonstrate that tumor growth of an engineered xenograft breast cancer model with hyaluronan-accumulating stroma can be dependent on hyaluronan and independent of CD44." (PMID 31762938, 2019).
breast carcinoma (continued). "hnRNPM mRNA levels were shown to correlate with aggressive breast cancer subtypes (basal and ER negative) and increased CD44 standard levels in breast cancer patients." (PMID 31666932, 2019). "All together, these data indicate that Notch inhibition may sensitize breast cancer to chemotherapeutics and that this involves a treatment-resistant BCSC population characterized by CD44+/CD24−/low cells." (PMID 30515368, 2018). "The importance of the ALDH+ and CD44+CD24− cell populations in breast cancer, and the comparative lack of knowledge about cells that express either or both markers in the normal breast, highlight the importance of further characterizing these populations." (PMID 29606612, 2018). "Furthermore, although CD44+/CD24-/low and ALDH1 were suggested as potential markers for breast cancer stem cells, their clinicopathologic and prognostic significance remains controversial." (PMID 29416796, 2018). "CD44 alternative splicing was differentially regulated during EMT, resulting in a switch in expression from CD44v to CD44s in human immortalized epithelial mammary cells and in a murine model of breast cancer progression." (PMID 29747682, 2018). "However, it is still unclear how the STAT3 pathway regulates the growth of CD44+/CD24– and ALDH1 positive breast cancer cells in TNBC tumor models." (PMID 30542507, 2018). "CSC markers include CD44+/CD24-/low in breast cancer, CD133+ in brain tumors and CRC, ALDH high in thyroid cancer, CD44+/α2β1high/CD133+ in prostate cancer, and numerous markers in other solid tumors." (PMID 29491834, 2018). "CD44 and CD24 expression was evaluated by double-staining immunohistochemistry technique in 165 cases of breast cancer tissues, and the cancer cell with CD44+/CD24-/low phenotype might be considered as BT-IC." (PMID 29423076, 2018). "This indicates that although other splicing factors might function to regulate CD44 alternative splicing under the control of SALL4, the SALL4 ‐ KHDRBS3 network contributes to stemness in basal‐like breast cancer." (PMID 29356399, 2018). "While researchers have demonstrated that CD44 and ALDH1 are critical biomarkers to identify BCSCs from breast cancer populations, our data suggested that the USP37 gene was significantly associated with CSC properties, such as self-renewal, treatment resistance and EMT phenotype as well." (PMID 30482232, 2018). "The presence of CD44 promotes tumorigenesis and metastasis in breast cancer, as does the absence of CD24." (PMID 30542507, 2018). "The TGFβ2 is identified as a CD44 downstream target that promotes EMT and breast cancer invasion." (PMID 29747682, 2018). "Although it is accepted that HER2-targeted therapy does not respond to HER2-negative breast cancer cells, our data indicated that trastuzumab treatment sensitized the radioresistant phenotype of CD44+/CD24–/low MCF7 cells." (PMID 29464036, 2018). "Furthermore, RNA sequencing data revealed that migratory TICs have a gene expression signature distinct from currently used markers in breast cancer (ALDHbr and CD24−/low/CD44+), allowing us to investigate new molecular regulators of TICs." (PMID 29321615, 2018). "Therefore, we analysed CD44 and CD24 expression in breast cancer cells treated with different concentrations of E2 using real‐time PCR." (PMID 30179299, 2018). "Increased ESRP1 can enrich for CD44v; thus, consistent with the prognostic ability ofESRP1, higher levels of CD44v, but not high CD44s or total CD44 levels, areprognostic markers for distant metastases in lung and breast cancer." (PMID 31069317, 2018). "We found more tumor cells with CD44+/CD24-/low phenotype could be detected in ER-positive and AR-positive breast cancers." (PMID 29423076, 2018). "Conversely, even 100 times more of CD44−/CD24+ breast cancer cells injected to NOD/SCID mice failed to form tumors." (PMID 30200262, 2018). "CD24−/CD44+ cells and ALDH1+cells are widely considered to be breast cancer stem cells." (PMID 30482232, 2018).
breast carcinoma (continued). "To follow up on our findings of epithelial-like and mesenchymal-like breast cancer stem cells, we isolated three cellular populations from reduction mammoplasty samples (n = 3 independent biological replicates) by flow cytometry: ALDH+, CD44+, and CD24+." (PMID 29606612, 2018). "Furthermore, some markers, such as E-cadherin, CD44 and CD24, which characterize the metastatic potential of human breast cancer cells, have been related to the molecular subtypes." (PMID 29632639, 2018). "But it also has been shown that ERα-positive breast cancer cells can secrete FGFR and EGFR ligands in response to estrogen, which can act as paracrine mediators to promote CSC activity and expand the fraction of CD44+ CD24−/lo cells." (PMID 29600163, 2018). "IGS was derived by comparing the gene-expression profile of CD44 + CD24−/low tumorigenic breast cancer cells with that of normal breast epithelium for predicting invasiveness." (PMID 29699511, 2018). "However, there is a small overlap between CD44+/CD24− and ALDH1 stem phenotypes, as well as less stem markers in differentiation of different breast cancer subtypes." (PMID 30482232, 2018). "To test the hypothesis, we first compared the expression of KLF4, ALDH1A1, ALDH1A3, CD44, and CD24 in human breast cancer samples available in TCGA database." (PMID 30038266, 2018). "In breast carcinoma CD44 positive and CD24 negative cells have been found in distant metastasis, therefore this phenotype is connected with a relapse after surgical resection." (PMID 28758908, 2017). "Ectopic BAG3 overexpression increased CD44+/CD24− CSC subpopulations, first-generation and second-generation mammosphere formation, indicating that BAG3 promotes CSC self-renewal and maintenance in breast cancer." (PMID 28703799, 2017). "In the MDA-MB-157 line the percentage of CD44+/CD24− cells did not change significantly upon WT1 loss, suggesting that down-regulation of WT1 does not affect the ‘stemness’ of breast cancer cells." (PMID 28345629, 2017). "Harrison and coworkers isolated BCSCs from breast cancer cell lines and primary breast cancer samples by sorting cells resistant to anoikis or cells containing markers of ESA+/CD44+/CD24low, and they found that Notch4 is specifically overexpressed in these BCSCs." (PMID 29069872, 2017). "This trend was more similar to that with the expression level of ALDH1 compared to CD44/CD24 in the cell lines, indicating that the expression level of ALDH1, rather than CD44/CD24, is positively correlated with the metastatic capacity of breast cancer." (PMID 29062075, 2017). "TRA2B showed the lowest prediction error over all subtypes and had previously been shown to be specifically induced in breast cancer, and more induced in invasive breast cancers compared to non-invasive breast cancers, perhaps by splicing CD44 isoforms." (PMID 28589855, 2017). "For example, the low or absent expression of CD24, in combination with high CD44, marks breast cancer stem cells." (PMID 28320418, 2017). "We have previously identified such a subset of breast cancer cells with high aldehyde dehydrogenase (ALDH) activity and expression of CD44, and demonstrated that these ALDHhiCD44+ cells have enhanced tumor-initiating and metastatic abilities both in vitro and in vivo." (PMID 28937653, 2017). "CD44/CD24 and ALDH1 are widely used cancer stem cell (CSC) markers in breast cancer." (PMID 29062075, 2017). "To investigate the association of c-Met with CSC markers such as ALDH1A1, ALDH1A3, CD44, and CD133 at gene expression levels in human breast cancers, we analyzed mRNA data and the clinical information of 1904 patients of breast cancers from cBioPortal for Cancer Genomics." (PMID 28966724, 2017).
breast carcinoma (continued). "Our data indicate that targeting IGFBP-3-dependent signaling pathways through gefitinib-FTY720 co-therapy may be effective in many basal-like breast cancers, and suggest tissue IGFBP-3 and CD44 measurement as potential biomarkers of treatment efficacy." (PMID 28778177, 2017). "For example, breast cancer cell lines reportedly lack PSGL-1, but express CD44, CEA, and PODXL, much like LS174T cells, which may imply that their rolling adhesion behavior exhibits similar trends on P-, E- and L-selectin." (PMID 29137366, 2017). "Controversially, in vivo xenograft analyses of breast cancer cell lines were unable to demonstrate ALDH+ or CD44+/CD24- CSC localization patterns, or demonstrate a correlation between the frequency of CD44+/CD24- CSCs and tumor metastasis as observed in patients with breast cancer." (PMID 29348905, 2017). "Given that ACTN4 might be a bridge connecting CSCs and metastasis function in breast cancer, particularly for the basal-like populations, we then investigated the expression of ACTN4 in ALDEFLOUR-positive cells or CD44+/CD24− populations." (PMID 29197410, 2017). "Previously, we found that miR-34a could inhibit the proliferation and migration of breast cancer by targeting B-cell lymphoma 2 (Bcl-2), silent information regulator 1 (SIRT1), E2F transcription factor 3 (E2F3) and CD44." (PMID 29037220, 2017). "To test this hypothesis, we investigated the role of CD44/CD24 ratio and ALDH1+ in the proliferation, tumorigenesis, migration and metastasis of breast cancer." (PMID 29062075, 2017). "Knockdown of ESRP1 activity in breast cancer cells restored the non-EMT-inducing isoform of CD44 and suppressed metastasis, evidence that ESRP1 acts as an oncogene." (PMID 28333948, 2017). "Our study indicated that DACH1 was inversely correlated with CD44 and CD44 might be a novel target of DACH1 in breast cancer." (PMID 28659634, 2017). "The present study sought to characterize the cell-surface and total protein expression of CD74 and CD44 in three human breast cancer cell lines types (CAMA-1, MDA-MB-231, MDA-MB-435) and in normal luminal 226LDM cells." (PMID 29190904, 2017). "We demonstrate that SMAD5 expression is required to induce a CD44+/CD24-/ALDH1+ breast cancer stem cell-like phenotype, suggesting that the Aurora-A/SMAD5 axis promotes chemoresistance through activation of stemness signalling in breast cancer." (PMID 29207686, 2017). "Given that CD44 and RGD-dependent integrins mediate the interaction between breast cancer cells and bone-derived OPN to influence migration to BMCM, we wanted to explore if these cell surface receptors also influence the stem-like phenotype of breast cancer cells." (PMID 28498874, 2017). "CD44+CD24- CSCs were observed in 77.8% (28/36) of luminal breast cancers while the number of these cells was not related on the luminal subtype: A, B HER2-, and B HER2+ (data not shown)." (PMID 28977854, 2017). "In the present study, we systematically investigated the expression of CD44, CD24 and ALDH1 in different subtypes of breast cancer cell lines, and explored their possible roles during cancer progression both at the cellular level and in the xenotransplanted mice model." (PMID 29062075, 2017). "The EpCAM+, CD24−, CD44+, and ALDH+ populations across different subtypes of breast cancers represent anatomically distinct BCSCs with respective EMT (epithelial-to-mesenchymal transition) and MET (mesenchymal-to-epithelial transition) gene expression profiles." (PMID 29258583, 2017). "As model system, we first assessed ZEB1, CD44, and LKB1 colocalization in two different breast cancer cell lines, the epithelial, luminal A subtype (MCF‐7) and the mesenchymal, metastatic type (MDA‐MB‐231), well representing the patients’ cohort in terms of primary tumor characteristics." (PMID 28700115, 2017). "The study suggests that CD44 and IGF2 are potential targets for breast cancer therapy." (PMID 28523716, 2017).
breast carcinoma (continued). "In accordance to this observation, TRIM28 reduction did not change the percentage of CSCs characterized by the CD44+CD24−/low phenotype in vitro in the tested breast cancer cell lines." (PMID 27845900, 2017). "The combination of high CD44/CD24 ratio and ALDH1+ may be a more accurate and reliable way to refine the definition of CSCs in breast cancer." (PMID 29062075, 2017). "Breast cancer Met-1 cells were transducted with a DACH1 expression vector resulting in an ∼4.5-fold increase in DACH1 expression and subsequent reduction of CSC markers CD44, KLF4 and MYC as well as EMT markers including FN1 and VIM by mRNA analysis." (PMID 28659634, 2017). "The present study has clearly demonstrated the occurrence of quantifiable colocalization between CD74 and CD44 in the plasma membrane of the breast cancer-derived cell lines CAMA-1, MDA-MB-231 and MDA-MB-435, suggesting interaction of these two molecules in breast cancer cells." (PMID 29190904, 2017). "Although we have demonstrated the correlation between CD44/CD24 ratio, ALDH1+ and the development, metastasis of breast cancer, whether these CSC markers are conserved and how they are dynamically changed during tumor progression have yet to be elucidated." (PMID 29062075, 2017). "The CD44/CD24 ratio and ALDH1 level were stable in the primary tumor and the distant metastases, and existed in CTCs, indicating the conservation of these two stem markers during the progression and metastasis of breast cancer." (PMID 29062075, 2017). "Additionally, growing evidence suggests that breast cancer cells that do successfully metastasize have a stem-like phenotype including high activity of aldehyde dehydrogenase (ALDH) and/or a CD44+CD24- phenotype." (PMID 28498874, 2017). "CD44 has been accepted as a CSC marker in a number of tumours, including gastric cancer, colorectal cancer, glioma, head and neck cancer and breast cancer." (PMID 27343550, 2017). "To explore the mechanistic basis for the elevated fraction of CD44+/CD24−/low phenotype observed in normal and breast cancer cell populations following irradiation, we combined in vitro experiments with a cellular automata (CA) model to test mechanistic alternatives." (PMID 27379202, 2016). "In breast cancer cells, activation of CD44s upregulates the transcriptional repressor ZEB1, which binds the promoter of the splicing factor ESRP1, resulting in self-sustaining ZEB1 and CD44 expression." (PMID 27009862, 2016). "Our experiments showed that WNT5A inhibited CD44 expression in breast cancer cells but not in HB2 cells." (PMID 27623766, 2016). "In contrast, enhanced miR-224 expression attenuated proliferation of MDA-MB-231 cells and growth of implanted breast cancers in vivo, but did not significantly change the frequency of CD44+CD24− CSCs in MDA-MB-231 cells." (PMID 27323393, 2016). "To date, not many studies have addressed the correlation between the CD44+/CD24low/− sub-population and disease progression in breast cancer patients, and only few of the studies analyzed patients diagnosed with different subtypes of disease." (PMID 27835603, 2016). "Nevertheless, we note that FRA1-promotion of cell migration likely involves other AP-1 target genes such as MMPs and adenosine receptor A2B (ADORA2B) as described in breast cancer, uPA in colon carcinoma, receptor tyrosine kinase AXL in bladder cancer, and CD44 and c-Met in mesothelioma." (PMID 27144339, 2016). "However, the ability of WNT5A to inhibit breast cancer cell migration and invasion is an EMT-independent mechanism that, at least in part, can be explained by decreased CD44 expression." (PMID 27623766, 2016). "CD44 also can interact with JAK2 and STAT3 to activate STAT3 in breast cancer." (PMID 27521216, 2016). "Furthermore, it has been reported earlier that hyaluronic acid stimulates the formation of a protein complex consisting of CD44, Hsp90, ErbB2 and ezrin, in TA3/St mammary carcinoma cells." (PMID 27029001, 2016).